CYP26A1 (cytochrome P450 family 26 subfamily A member 1)
Description:
A cytochrome P450 monooxygenase involved in the metabolism of retinoates (RAs), the active metabolites of vitamin A, and critical signaling molecules in animals. RAs exist as at least four different isomers: all-trans-RA (atRA), 9-cis-RA, 13-cis-RA, and 9,13-dicis-RA, where atRA is considered to be the biologically active isomer, although 9-cis-RA and 13-cis-RA also have activity (Probable). Catalyzes the hydroxylation of atRA primarily at C-4 and C-18, thereby contributing to the regulation of atRA homeostasis and signaling. Hydroxylation of atRA limits its biological activity and initiates a degradative process leading to its eventual elimination (Probable). Involved in the convertion of atRA to all-trans-4-oxo-RA. Able to metabolize other RAs such as 9-cis, 13-cis and 9,13-di-cis RA (By similarity). Can oxidize all-trans-13,14-dihydroretinoate (DRA) to metabolites which could include all-trans-4-oxo-DRA, all-trans-4-hydroxy-DRA, all-trans-5,8-epoxy-DRA, and all-trans-18-hydroxy-DRA (By similarity). May play a role in the oxidative metabolism of xenobiotics such as tazarotenic acid.
Synonyms: CYP26; P450RAI1; P450RAI; CP26
Tractability: Small molecule: a drug acting on it is in phase 2 or 3 trials; a high-quality ligand is known; it belongs to a druggable protein family. Antibody: UniProt places it where antibodies can reach, with medium confidence. PROTAC: a small molecule that binds it is known.
Target class: Cytochrome P450 family 26; Cytochrome P450; Cytochrome P450 26A1; Enzyme; Cytochrome P450 family 26A
Chemical probes: PD080857, PD082385, PD083599, PD084139
Gene: Protein-coding gene on chromosome 10 (93,073,475 to 93,077,885, forward strand). Ensembl gene ENSG00000095596.
Subcellular location: Endoplasmic reticulum membrane; Microsome membrane
Pathways (Reactome):
Metabolism: Vitamins
Signal Transduction: RA biosynthesis pathway
Gene Ontology:
Molecular function: all-trans retinoic acid 18-hydroxylase activity; oxidoreductase activity, acting on paired donors, with incorporation or reduction of molecular oxygen, NAD(P)H as one donor, and incorporation of one atom of oxygen; retinoic acid 4-hydroxylase activity; retinoic acid binding; heme binding; oxygen binding; all-trans retinoic acid 4-hydrolase activity; iron ion binding; monooxygenase activity; oxidoreductase activity, acting on paired donors, with incorporation or reduction of molecular oxygen
Biological process: retinoic acid catabolic process; retinoic acid metabolic process; xenobiotic metabolic process; central nervous system development; negative regulation of retinoic acid receptor signaling pathway; vitamin metabolic process; kidney development; response to retinoic acid; response to vitamin A
Cellular component: endoplasmic reticulum membrane
Genetic constraint (gnomAD): Loss-of-function variants: 27 observed, 26.08 expected, observed/expected ratio (o/e) 1.04, 90% interval 0.76 to 1.43. The upper end of that interval is the gene's LOEUF score, 1.43, which puts it in group 5 of 6, group 1 being the genes least tolerant of losing a copy. Missense variants: 464 observed, 449.98 expected, observed/expected ratio (o/e) 1.03, 90% interval 0.95 to 1.11. Synonymous variants: 184 observed, 183.36 expected, observed/expected ratio (o/e) 1, 90% interval 0.89 to 1.13.
Homologues: Orthologues: chimpanzee CYP26A1 (99% identical), dog CYP26A1 (95% identical), pig CYP26A1 (95% identical), guinea pig CYP26A1 (94% identical), rabbit CYP26A1 (94% identical), mouse Cyp26a1 (94% identical), rat Cyp26a1 (92% identical), macaque CYP26A1 (90% identical), tropical clawed frog cyp26a1 (70% identical), zebrafish cyp26a1 (68% identical). Paralogues in human: CYP26C1 (46% identical), CYP26B1 (44% identical).
Diseases named in the same sentence as CYP26A1 in open-access papers:
CYP26A1 is named in the same sentence as 75 diseases in open-access papers, as found by Europe PMC text mining. Sharing a sentence is not in itself a finding about the gene and the disease. The quoted sentences say what the papers report.
breast carcinoma (7 papers, 2005 to 2022). "Particularly, CYP26A1, the gene encoding the cytochrome P450 enzyme specifically involved in metabolic inactivation of retinoic acid, was highly expressed in breast cancers and showed oncogenic characteristics suggesting a link between intracellular retinoic acid status and tumorigenesis." (PMID 27298823, 2016). "Breast cancer cells overexpressing CYP26A1 displayed oncogenic properties, improved cell survival, higher resistance to anoikis and enhanced tumorigenicity and metastatic potential." (PMID 33809117, 2021). "A report noted that RA can induce CYP26A1 expression in neuroblastoma, breast cancer, and lung cancer cell lines." (PMID 25839051, 2015). "In breast cancer or colon cancer cells, CYP26A1 gene expression can be induced via the receptor of vitamin A." (PMID 25839051, 2015). "In retinoid-sensitive neuroblastoma, lung and breast cancer cell lines, direct inhibition of retinoid-induced RARβ2 expression blocked induction of only one of eight retinoid target genes (CYP26A1)." (PMID 16012519, 2005). "Consistently, knocking down of RA-induced RARβ2 expression partly blocked RA-induced CYP26A1 expression across RA-sensitive neuroblastoma, lung and breast cancer cells." (PMID 16012519, 2005). "RA-induced expression of liganded RARβ2 directly regulated CYP26A1 in RA-sensitive and -resistant neuroblastoma, lung and breast cancer cells." (PMID 16012519, 2005). "Since the level of histone acetylation, and conversely deacetylation, can influence gene transcription, the effect of the histone deacetylase (HDAC) inhibitor, TSA on RARβ2 and CYP26A1 expression in RA-resistant lung and breast cancer cells was investigated." (PMID 16012519, 2005). "CYP26A1 also regulates the expression of the actin-bundling protein fascin by modulating the levels of RA thereby affecting the malignant behaviour of CYP26A1 expressing breast cancer cells." (PMID 33809117, 2021). "Recently, the RA metabolizing enzyme CYP26A1 (cytochrome P450, family 26, subfamily A, polypeptide 1) has been shown to promote the survival and oncogenic potential of breast carcinoma cells, indicating a possible oncogenic function of CYP26A1 in breast carcinogenesis." (PMID 25294402, 2014). "However, forced overexpression of RARβ2 activated CYP26A1 transcription in RA-resistant breast cancer cells when the RARβ2 ligand, RA, was added." (PMID 16012519, 2005). "Additionally, 42% (27/65) of tissue samples removed from breast cancer patients had CYP26A1 overexpression; CYP26A1 overexpression may induce intracellular RA consumption, thus pushing the cells toward tumorigenicity; CYP26A1 may be recommended as a candidate oncogene." (PMID 25839051, 2015). "Four of 12 target genes (RARβ2, CYP26A1, CRBP1, and RGS16) were upregulated by more than two-fold in both the RA-sensitive lung and breast cancer cells." (PMID 16012519, 2005). "The pattern of retinoid responsiveness for six of 13 target genes (RARβ2, CYP26A1, CRBP1, RGS16, DUSP6, EGR1) correlated with phenotypic retinoid sensitivity, across a panel of retinoid-sensitive or -resistant lung and breast cancer cell lines." (PMID 16012519, 2005). "Furthermore, CYP26A1 was found to be a retinoid-responsive gene in retinoid-sensitive NB in MYCN transgenic mice and lung and breast cancer cell lines." (PMID 36231133, 2022). "Thus, in both mouse embryonic fibroblasts and human breast cancer cells, RA treatment activates the p38 MAPK pathway to enhance transcription of Cyp26A1, one of the RA target genes." (PMID 31682623, 2019). "In noncompetitive RT–PCR, we detected weak RARβ2 and CYP26A1 expression in the RA-resistant breast cancer cell line, MDA-MB-231, after treatment with aza-CdR and aRA, in a dose-dependent manner." (PMID 16012519, 2005).
neuroblastoma (7 papers, 2005 to 2022). Neuroblastoma (NB) is the most common solid, extracranial childhood tumor. "Retinoid treatment of MYCN transgenic mice bearing neuroblastoma altered the expression of five of nine target genes examined (RARβ2, CYP26A1, CRBP1, DUSP6, PLAT) in neuroblastoma tumour tissue in vivo." (PMID 16012519, 2005). "Additionally, we found that 13-cis-RA only marginally upregulated CYP26A1 expression in neuroblastoma tissues in vivo, while inducing RARβ2 expression to a similar extent as in vitro." (PMID 16012519, 2005). "CYP26A1 mRNA induction has been reported in skin, intestinal, liver, APL and neuroblastoma cells treated with RA, and CYP26A1 protein is highly expressed in normal human skin." (PMID 17486130, 2007). "Our data suggest that RA-induced changes in the expression of RARβ2, CYP26A1, CRBP1, RGS16, DUSP6, and EGR1 may be necessary for the retinoid anticancer signal in neuroblastoma, breast and/or lung cancer cells." (PMID 16012519, 2005).
colon cancer (4 papers, 2005 to 2023). "We analyzed gene expression of Cyp26a1, Cyp26b1 and Cyp26c1 in N-MFs and CAFs isolated colon cancer patients." (PMID 37185128, 2023). "This inter-relationship is in agreement with earlier studies, which showed that exogenous RARβ2 overexpression in RA-resistant HCT-116 colon cancer cells partially restored RA-induced CYP26A1 expression." (PMID 16012519, 2005). "A previous study found that the expression of CYP26A1 may be induced by the RA receptors in breast and colon cancer cells." (PMID 33233443, 2020).
hepatocellular carcinoma (4 papers, 2012 to 2022). A malignant tumor that arises from hepatocytes. "Four thousand four hundred seventy-nine potential pathogenic genes (including MYH2, FGF21, and CYP26A1) for hepatocellular carcinoma were integrated, and cointerpretation analysis was performed with a correlated phenotype." (PMID 34651050, 2021). "Retinol and retinal dose- and time-dependently induced the expression of RA responsive Cyp26a1 gene in hepatocytes and hepatoma cells." (PMID 23028851, 2012). "Our findings were consistent with those of previous studies with regards to the significant downregulation of CYP26A1 in hepatocellular carcinoma tissue compared to paired-matched non-tumor tissue, using quantitative mRNA expression analysis." (PMID 33233443, 2020). "To screen for cultured cell lines which we can study the effects of retinoid metabolism on the expression of RA responsive gene, we analyzed the expression of Cyp26a1 mRNA and CYP26A1 protein in response to ROL, RAL and RA treatments in HL1C rat hepatoma cells." (PMID 23028851, 2012).
pharyngeal cancer (4 papers, 2015 to 2020). "Our results have revealed an important insight into the impact of BQ chewing on the two single nucleotide polymorphisms (SNPs), rs2068888 or rs4418728, of CYP26A1, and oral and pharyngeal cancer risk (rs2068888, odds ratio (OR) = 5.0; 95% CI = 1.1–22.1)." (PMID 33233443, 2020). "Two SNPs, rs2068888 and rs4418728, in the downstream of CYP26A1 were genotyped to examine association with the occurrence of oral and pharyngeal cancers." (PMID 33233443, 2020). "This study is the first to demonstrate that lower levels of CYP26A1 expression are significantly associated with the risk of oral and pharyngeal cancers, showing a relationship between the levels of CYP26A1 and SNP polymorphism." (PMID 33233443, 2020). "In order to exclude the differences in CYP26A1 expression between individuals, we used the same patients with paired tissue to confirm the association between CYP26A1 expression and the occurrence risk of oral and pharyngeal cancers." (PMID 33233443, 2020). "Carriers of CYP26A1 SNP, rs2068888 (G/G)/rs4418728 (G/G) and who have lower levels of CYP26A1 expression are associated with an increased risk of oral and pharyngeal cancers." (PMID 33233443, 2020). "We suggest that CYP26A1 plays a novel biomarker in modulating the BQ dependent pathogenic effect on the risk of oral and pharyngeal cancers, particularly individuals with at-risk genotype and lower expression (mRNA levels < 0.069) of CYP26A1." (PMID 33233443, 2020). "BQ chewers with the CYP26A1 rs4411227 C/C+C/G genotype and C allele showed an increased risk of oral and pharyngeal cancer (adjusted odds ratio (aOR) = 2.30 and 1.93, respectively)." (PMID 25839051, 2015). "We hypothesized that lower levels of CYP26A1 mRNA expression can be utilized a clinically biomarker causes oral and pharynx cancers." (PMID 33233443, 2020). "BQ chewers with the CYP26A1 rs4411227 C allele and CYP26B1 rs3768647 G allele had the highest risk of oral and pharyngeal cancer compared with the subjects carrying the CYP26A1 rs4411227 G allele and CYP26B1 rs3768647 C allele (aOR = 29.91; 95% CI = 10.75–83.23)." (PMID 25839051, 2015). "BQ chewers with the CYP26A1 rs4411227 C allele and CYP26B1 rs9309462 C allele had the highest risk of oral and pharyngeal cancer compared with the subjects carrying the CYP26A1 rs4411227 G allele and CYP26B1 rs9309462 T allele (aOR = 10.03; 95% CI = 1.05–95.60)." (PMID 25839051, 2015). "In conclusion, we demonstrated that carriers of downregulated CYP26A1 expression are susceptible to an increased risk of oral and pharyngeal cancers and the joint effects of genetic SNPs (rs2068888 (G/G) or rs4418728 (G/G)) and BQ use in oral and pharyngeal cancer patients." (PMID 33233443, 2020). "Therefore, this study was designed to determine whether CYP26A1 variants play an important role in determining the risk of oral and pharyngeal cancer occurrence." (PMID 33233443, 2020). "The imbalance in RA signaling may be associated with occurrence of oral and pharyngeal cancer, and the low expression of RARs, lower levels of cellular RA, reduced transcription of RA-metabolizing enzyme CYP26A1, and changes in RA metabolism may be involved in the carcinogenic pathway." (PMID 33233443, 2020). "Therefore, we hypothesize that the CYP26A1 expression may be associated with RA metabolism via RA receptors, and that lower RA levels may increase the risk of oral and pharyngeal cancers." (PMID 33233443, 2020). "Our findings showed that the downregulation of CYP26A1 mRNA and protein expression are more frequently observed in cancerous tissues than adjacent normal tissues in patients with oral and pharynx cancers (p < 0.01)." (PMID 33233443, 2020). "In clinical tissues, we found a significant downregulation of CYP26A1 in oral and pharyngeal cancer tissues compared with their adjacent tissues." (PMID 33233443, 2020).
pharyngeal cancer (continued). "In conclusion, this study suggested that BQ chewers with ROS related to CYP26A1 and CYP26B1 polymorphisms are associated with an increased risk of oral and pharyngeal cancer and OPMDs." (PMID 25839051, 2015). "In this study, we found that the downregulation of CYP26A1 expression may play an important role in the occurrence of oral and pharyngeal cancers." (PMID 33233443, 2020). "Thus, the specific aim of this association study was to investigate the role of CYP26 family (CYP26A1 and CYP26B1) single nucleotide polymorphisms (SNPs) in the risk of OPMDs and oral and pharyngeal cancers." (PMID 25839051, 2015). "We hypothesized that the lower levels of CYP26A1 expression in oral and pharyngeal cancer tissue may be due to lower RA levels, reduced retinoid signaling due to RXR phosphorylation, or an unidentified factor that may be specifically expressed in tumor tissues." (PMID 33233443, 2020). "However, no study has yet confirmed variants of CYP26A1 was associated with the risks of oral and pharyngeal cancers." (PMID 33233443, 2020). "However, to the best of our knowledge, the expression of CYP26A1 in oral and pharyngeal tumor tissues compared to their adjacent normal tissues in humans has not yet been reported in oral and pharynx cancer studies." (PMID 33233443, 2020).
colorectal cancer (3 papers, 2014 to 2020). A primary or metastatic malignant neoplasm that affects the colon or rectum. "In contrast, a previous study have found that CYP26A1 expression is upregulated in colorectal cancer." (PMID 33233443, 2020). "The intensity of immunostaining was significantly higher in primary colorectal cancer compared with normal colonic mucosa for CYP26A1 (p = 0.002), CYP26B1 (p<0.001) and LRAT (p<0.001)." (PMID 24608339, 2014). "This study has shown that the retinoic acid metabolising enzymes CYP26A1, CYP26B1 and LRAT are significantly overexpressed in colorectal cancer and that CYP26B1 and LRAT are significantly associated with prognosis both in the total cohort and in those tumours which are mismatch repair proficient." (PMID 24608339, 2014). "A recent study demonstrated that the retinoic acid-metabolizing enzymes CYP26A1 and CYP26B1 are significantly overexpressed in colorectal cancer tissue." (PMID 25839051, 2015). "Comparison of CYP26A1, CYP26B1 and LRAT expression in normal colonic mucosa, primary colorectal cancer and lymph node metastasis." (PMID 24608339, 2014). "This study has defined the expression profile of the retinoic acid metabolising enzymes CYP26A1, CYP26B1 and CYP26C1 which are members of the P450 family of enzymes and LRAT in a large cohort of well characterised colorectal cancers." (PMID 24608339, 2014). "The relationship of the expression of CYP26A1, CYP26B1 or LRAT and survival in MMR proficient and defective colorectal cancers." (PMID 24608339, 2014). "The CYP26 enzymes have been proposed as anti-cancer drug targets and the increased expression of CYP26A1 and CYP26B1 in colorectal cancer would suggest that these enzymes may be relevant therapeutic targets in this type of tumours." (PMID 24608339, 2014). "Epidemiological evidence has also proposed targeting of retinoids and the retinoic acid pathways for chemoprevention of colorectal cancer and the increased expression of CYP26A1 and CYP26B1 in colorectal cancer would indicate that targeting these enzymes may be a useful approach." (PMID 24608339, 2014).
endometriosis (3 papers, 2017 to 2019). The growth of functional endometrial tissue in anatomic sites outside the uterine body. "CYP26A1 encodes for a retinoic acid metabolizing enzyme, and maps close to a region of the genome identified to be significantly linked to endometriosis in family-based analyses." (PMID 29099281, 2017). "Several genes found to be dysregulated in the endometrium of endometriosis patients are known progesterone targets (Foxo1a, Mig6 and Cyp26a1) and their overall pattern of expression suggested prolongation of the proliferative phase." (PMID 30992697, 2019). "In addition, the CYP26A1 mRNA level in premenopausal endometria was more than 10‐fold higher than that in postmenopausal endometriosis." (PMID 27860312, 2017). "However, in women with moderate or severe endometriosis, CYP26A1 was significantly down‐regulated in both the early secretory and midsecretory endometrium relative to controls 7, suggesting that CYP26A1 has important functions in both uterine physiology and pathology." (PMID 27860312, 2017).
head and neck cancer (3 papers, 2014 to 2020). A primary or metastatic malignant neoplasm affecting the head and neck. "Moreover, high levels of CYP26A1 expression and RA catabolic activity have been detected in breast epithelial adenocarcinoma tissue culture, head and neck cancer squamous cells, and acute promyelocytic leukemia cells." (PMID 33233443, 2020). "Similarly, recent studies indicated that the increased expression of CYP26A1 genes was related to head and neck cancer." (PMID 25839051, 2015). "We immunohistochemically examined the expression of CYP26A1 in cervical squamous cell carcinoma (SCC) and its precursors, including low- and high-grade squamous intraepithelial lesions (LSIL and HSIL, respectively), as well as head and neck cancer (HNC)." (PMID 25294402, 2014).